INS (insulin)
Diseases named in the same sentence as INS in open-access papers (continued):
Sharing a sentence is not in itself a finding about the gene and the disease.
Infertility (continued). "In PCOS, elevated exosomal DENND1A.V2 protein promotes insulin and MAPK signaling, causing insulin resistance and infertility." (PMID 39849635, 2025). "Randomized trials comparing myo-inositol with other antioxidants, insulin-sensitizing agents, and ovulation-inducing medications are necessary to determine its role in infertility treatment." (PMID 41041518, 2025). "The results of our study showed elevated levels of DHEAS, testosterone, insulin, and prolactin, highlighting the intricate hormonal imbalances that contribute to infertility in PCOS." (PMID 40802395, 2025). "In other words, insulin, by stimulating the response of ovarian follicles to gonadotropin, contributes to developing anovulatory infertility." (PMID 40474898, 2025). "This network meta-analysis compared the effects of different exercise modalities on anti-insulin stability and testosterone values in women with infertile PCOS." (PMID 40941484, 2025). "Proper insulin sensitivity is paramount for testicular function, as insulin resistance disrupts the metabolic activity of Sertoli and Leydig cells, providing a mechanistic link between metabolic dysfunction and infertility." (PMID 41150585, 2025). "In women, increases in the genetically determined levels of fasting insulin were related to greater odds of infertility (+1 log(pmol/l): odds ratio 1.60, 95% CI 1.17 to 2.18, P-value = 0.003)." (PMID 37949105, 2024). "When defective, insulin signaling in the female reproductive system can lead to subfertility or infertility due to ovarian and/or uterine dysfunction." (PMID 38790245, 2024). "Earlier studies in Drosophila suggested that TOR acts upstream of Spargel in the insulin signaling pathway and that inactivation of TOR in the ovary, like loss of Spargel, causes oogenesis defects leading to infertility." (PMID 37369430, 2023). "For anovulatory infertility, medications like clomiphene citrate (CC), metformin, and insulin-sensitizing drugs can be used to induce ovulation." (PMID 37859871, 2023). "The resulting OS induces prolonged anovulation, aberrant ovarian extracellular remodeling, cyst development, and an inflammatory environment that worsens insulin resistance, all of which contribute to infertility." (PMID 36835217, 2023). "To answer this question, we conducted a network meta-analysis and systematic review to comprehensively evaluate the effects of first-line ovulation induction agents and insulin sensitizers in infertile women with PCOS." (PMID 36869381, 2023). "The results of a study showed that improvement of insulin sensitivity increases pregnancy rate in infertile PCOS women." (PMID 36246893, 2022). "Some randomized controlled trials have reported a therapeutic effect of PA on infertility that acts through systemic effects such as increased immune function, insulin resistance, and circulating sex hormones." (PMID 35606876, 2022). "BAT transplantation was also reported to enhance endogenous BAT activity and to increase the level of circulating adiponectin and insulin sensitivity, thereby positively affecting acyclic polycystic ovaries, hyperandrogenism and infertility of rats with PCOS." (PMID 36289764, 2022). "Further studies with a larger sample size are needed to investigate the relationship between betatrophin and insulin resistance and lipid metabolism, and its effects on infertility treatment outcomes." (PMID 35308327, 2022). "One hundred two women who underwent treatment for infertility were enrolled and evaluated for insulin resistance." (PMID 36051734, 2022). "Over half reported infertility (n = 248, 60.2%, ± 4.73) and insulin imbalances (n = 251, 55.7% ± 4.58), and nearly half reported feeling depressed as a result of having PCOS (n = 200, 44% ± 4.56)." (PMID 33731099, 2021). "Clinical treatment of patients with PCOS ovulatory dysfunction infertility is mainly treated with ovulation-promoting drugs, insulin sensitizer, hyperandrogenemia drugs and other drugs Healing." (PMID 33725936, 2021).
Infertility (continued). "Of the subjects, 5 (3.5%) reported a history of using medications other than infertility medications, including levothyroxine in 4 (2.8%) and insulin in 1 (0.7%)." (PMID 32259004, 2020). "A number of ovulation induction treatments are commonly used in infertility treatments: estrogen antagonists, insulin sensitizing agents, gonadotrophins, and GnRH analogs." (PMID 32279157, 2020). "In women, a high AGE diet directly correlates with high levels of androgens, anti-Müllerian hormone, insulin, and androstenedione, promoting ovarian dysfunction and/or infertility." (PMID 31861217, 2019). "The underlying cause of this disease includes chronic anovulation, increased androgen level in the blood, and decreased sensitivity to insulin leading to abnormal uterine bleeding, hirsutism, and infertility." (PMID 31488983, 2019). "As a consequence, suppression of insulin/IGF signaling in granulosa cells leads to infertility, whereas suppression in SCs leads to males which, although able to produce offspring, show a dramatic reduction in their final pool of SCs." (PMID 31505893, 2019). "PCOS is most often diagnosed in adolescents struggling with menstrual issues or women with infertility; combine those issues with hirsutism, high insulin levels, weight-gain, and acne, and this leads to a vulnerable and frustrated population." (PMID 30373317, 2018). "This trial was aimed to determine the effects of chromium supplementation on gene expression of insulin, lipid, and inflammatory markers in infertile women who suffered from PCOS and were candidate for IVF." (PMID 30546347, 2018). "Overall, the findings of this trial supported that 50,000 IU vitamin D supplementation every other week for 8 weeks had beneficial effects on insulin metabolism, and some parameters of lipid profiles among infertile women with PCOS who were candidate for IVF." (PMID 30286768, 2018). "According to our best knowledge, nothing has been published about the effects of chromium supplementation on gene expression of insulin, lipid, and inflammatory markers in infertile women with PCOS who were candidate for IVF." (PMID 30546347, 2018). "Overall, the findings of this trial supported that 50,000 IU vitamin D supplementation every other week for 8 weeks had beneficial effects on insulin metabolism, and lipid profile of infertile women with PCOS who are candidate for IVF." (PMID 30286768, 2018). "It was indicated that there is a positive relationship between high glycemic index foods and infertility, and also there is a beneficial effect of higher intake of whole grains in insulin sensitivity and regulating blood glucose." (PMID 29662966, 2017). "This can clarify the positive correlation between seminal glucose and seminal insulin levels, and the significant increase in spermatozoa insulin gene expression in the infertile MS group with a significant positive correlation with seminal glucose." (PMID 27891185, 2016). "Others have shown that insulin signaling in the pituitary gonadotroph or ovarian theca cell contributes to infertility in female DIO mice." (PMID 25946091, 2015). "High insulin level was found to increase the testosterone biosynthesis of human ovarian thecal cells deriving from insulin resistant, infertile women with polycystic ovarian syndrome (PCOS)." (PMID 23061769, 2013). "Due to major implication ofinsulin resistance in PCOS pathogenesis, insulin reduction strategies were studied as a possible treatment for infertility in PCOS patients." (PMID 20108521, 2008). "Additionally, elevated levels of DHEAS, testosterone, insulin, and prolactin highlight the intricate hormonal imbalances that contribute to infertility in this population." (PMID 40802395, 2025). "The use of the insulin sensitizer metformin was reported by 34.9% of infertile patients." (PMID 39862270, 2025).
Infertility (continued). "However, a recent study has confirmed that in the context of ART, infertile non-PCOS women with IR showed a higher clinical miscarriage, leading to fewer live births compared with the insulin-sensitive infertile patients." (PMID 41450577, 2025). "However, HMB hospitalizations with age ≤ 40 years were associated with all the risk factors including DM, MS, insulin use, IBD, and infertility." (PMID 38783294, 2024). "Importantly, infertile women showed significantly lower eGDR values (8.11 ± 0.23 vs 9.25 ± 0.08, P <0.001), suggesting that they have reduced insulin sensitivity." (PMID 39600947, 2024). "In a systematic review by McGrice and Porter, it was confirmed that reducing carbohydrate load could reduce circulating insulin levels, improve hormonal imbalance and result in ovulation resumption to improve pregnancy rates in infertile women." (PMID 37405618, 2023). "We found evidence that berberine intake may improve menstrual patterns in PCOS infertile women with chronic anovulation up to the point of regaining regular menses and ovulation second to an insulin resistance decrease." (PMID 36676074, 2023). "Moreover, the infertility of the Akita diabetic mice can be restored by exogenous insulin treatment." (PMID 35121747, 2022). "The infertility that affects women with PCOS is thought to be partly attributable to IR, which affects up to 70% of those with PCOS and is linked to profoundly abnormal insulin activity in the reproductive system." (PMID 33709493, 2021). "Nonetheless, it has been shown that overexpression of INS in LCs reduces the number of germ cells and gradually leads to infertility in mice, and that insulin induces the expression of DAX1 (officially NR0B1) in LCs, which in turn inhibits testicular steroidogenesis both in vivo and in vitro." (PMID 31505893, 2019). "The results of this trial demonstrated the beneficial effects of 50,000 IU vitamin D supplementation every other week for 8 weeks on improving insulin metabolism and some of the markers of lipid profile among infertile women diagnosed with PCOS who were candidate for IVF." (PMID 30286768, 2018). "Participants in the lifestyle intervention group had lower body weight, waist- and hip circumference, blood pressure, fasting glucose and insulin levels, insulin resistance, and a higher physical QoL compared to women who directly started infertility treatment." (PMID 29324776, 2018). "Our present findings highlight the importance of an increased knowledge of the action of insulin on endometrial function, and may illuminate possible reasons to unexplained infertility." (PMID 28135285, 2017). "However, the modest proportion mediated (9.61%) suggests that additional mediators, such as insulin resistance, lipid metabolism, and hormonal milieu, may also contribute to the lifestyle-infertility relationship." (PMID 41141251, 2025). "Genetic instruments suggest that higher fasting insulin may increase infertility in women." (PMID 37949105, 2024). "Furthermore, infertility treatment using assisted reproductive technology may be a possible predictive factor for insulin therapy in women with GDM." (PMID 31656196, 2019). "However, Metformin as an insulin sensitizer is widely used by infertile women with PCOS, which could have reduced ovarian androgens, luteinizing hormone and sex hormone binding globulins." (PMID 31367235, 2019). "None of the infertility parameters was associated with insulin therapy in this group." (PMID 31656196, 2019). "Therefore, this study was conducted to determine the effects of vitamin D supplementation on the levels of anti-Müllerian hormone (AMH), metabolic profiles, and gene expression of insulin and lipid metabolism in infertile women with PCOS who were candidate for in vitro fertilization (IVF)." (PMID 30286768, 2018).
Infertility (continued). "Thus, the amelioration of ovulation problems achieved by insulin sensitizers (i.e., troglitazone, metformin) may alleviate emotional distress due to infertility and thus contribute to the improvement of the HRQoL of PCOS patients." (PMID 27553217, 2016). "Screening via the STRING platform and Cytoscape 3.10.1 software yielded four core targets for ATBC-induced infertility-HSP90AA1, PIK3CA, CASP3, HRAS-and four core targets for icariin treatment-IL6, TNF, STAT3, and INS." (PMID 41898778, 2026). "A study found that combined letrozole and metformin treatment improved insulin sensitivity by lowering HOMA-IR, insulin levels, and lipid profiles in infertile women with PCOS, while also enhancing ovarian function." (PMID 40650016, 2025). "The improved biochemical measures of PCOS included androgen levels, lipids, HOMA-IR, blood glucose, insulin, LH/FSH ratio, DHEAS, SHBG, AFC, and AMH, while the improved symptoms of PCOS were irregular menstruation, infertility, OHSS, and weight gain." (PMID 40944281, 2025). "Factors such as older age, elevated DHEAS levels, higher insulin, HOMA-IR, triglycerides, and prolactin levels were notably different between the two groups, all of which contribute to infertility in women with PCOS." (PMID 40802395, 2025). "Most of the CVD outcomes remained significantly associated with HMB even after additionally accounting for individual components of MS, insulin use, DM, IBD, infertility, and anemia among hospitalizations of young women." (PMID 38783294, 2024). "The reproductive subtype was identified by comparatively low body mass index (BMI) and insulin levels, as well as greater levels of LH and sex hormone-binding globulin (SHBG) and more severe infertility and irregular menstruation." (PMID 38389707, 2024). "Long-term exercise for women with infertility can decrease insulin and free androgen levels, leading to HPA mediating the recovery of infertility." (PMID 35606876, 2022). "Given the correlation between leptin, obesity, insulin action and reproductive functions, we hypothesized that plasma leptin and sOB-R levels, and also LEP/LEPR variants might be associated with PCOS as well as infertility and recurrent pregnancy loss (RPL) in PCOS patients." (PMID 34407095, 2021). "Despite similar serum levels of FBG, PCOS-Inf and PCOS-RPL subgroups had significantly higher levels of fasting insulin and HOMA-IR, when compared to the control group, with higher levels in the infertile subgroup." (PMID 32330176, 2020). "The expression pattern of cumulus cells of infertile PCOSpatients in an IVF program was studied and comparedbased on their insulin sensitivity." (PMID 30507086, 2019). "Lipoprotein ratios, particularly TG/HDL-C, are directly correlated with insulin levels and can be used as a marker of IR (HOMA-IR) in infertile PCOS patients." (PMID 27123197, 2016). "Thus, resistance to insulin or leptin in Kiss1 neurons could lead to infertility." (PMID 25946091, 2015). "In their 2024 study, they demonstrated that supplementation with 12 mg/day for eight weeks in infertile women with PCOS significantly improves systemic metabolic parameters, with a reduction in fasting glucose and insulin, the HOMA-IR index, and LDL cholesterol, along with an increase in HDL." (PMID 41596351, 2026). "Additionally, elevated levels of DHEAS, testosterone, insulin, prolactin, triglycerides, TG/HDL, AIP, and LCI in the infertile cohort underscore the multifactorial nature of infertility in PCOS." (PMID 40802395, 2025). "Additionally, the upregulation and downregulation of FF-exosome miRNAs related to cell signaling pathways such as the PI3K/Akt, TGF-β, insulin, IGF, Wnt, and Notch lead to infertility and aging." (PMID 39849635, 2025). "Additionally, the Festival Group exhibited a shorter mean duration of infertility, lower proportion of tubal factor infertility as the main indication for ART, lower fasting insulin levels, and fewer cycles involving fresh ET." (PMID 40604013, 2025).
Infertility (continued). "Our findings suggest a critical relationship between the dysregulation of insulin signaling pathways and endometrial function, which could have profound implications for the treatment and management of PCOS-related infertility." (PMID 38310251, 2024). "The continuous increase in insulin levels stimulates the ovaries to secrete excessive androgens and decrease hepatic SHBG, ultimately aggravating abnormalities in the hypothalamus-pituitary-ovarian axis, ovulation disorders and infertility." (PMID 37974132, 2023). "A large body of evidence supports the role of carbohydrates in fertility as well, and dietary adjustments to reduce insulin secretion represent an intriguing non-pharmacological perspective to counteract infertility." (PMID 35565885, 2022). "Our next goal was to evaluate whether the inhibition of androgen-AR activation with flutamide could rescue the gravid uterine defects and infertility induced by combined exposure to DHT and INS (which mimic the typical PCOS features)." (PMID 34180022, 2021). "This study demonstrated that 50,000 IU vitamin D supplementation every other week for 8 weeks resulted in significant decreases in serum AMH, insulin levels and HOMA-IR score, and a significant increase in QUICKI in infertile women with PCOS who were candidate for IVF." (PMID 30286768, 2018). "The ovarian dysfunction and infertility observed in the DIO mouse model may be due to alterations in testosterone and LH in addition to insulin." (PMID 25780937, 2015). "Based on this, any agents that can increase insulin sensitivity, such as thiazolidinediones (TZDs) and glucagon-like peptide 1 receptor agonist (GLP-1RA), are highly attractive and used as one of the first-line pharmacological treatments for infertile PCOS women." (PMID 36869381, 2023). "Clearly, this was not the case in this study, where all of the subjects were non-obese and not insulin resistant, thus suggesting that PCBs may have a more direct role than previously realized or represent a biological marker for unexplained infertility." (PMID 37850102, 2023). "For the treatment of infertile with PCOS, Western medicine mainly takes drugs (including these types of drugs: ovulation-promoting drugs, drugs to reduce androgen levels, drugs to improve insulin levels, etc.)and surgical treatment, and even the use of assisted reproductive technology." (PMID 35089214, 2022). "Consequently, POMC neurons as a target of leptin/insulin actions were shown to be important for fertility, as IR/LEPR-POMC KO mice exhibit lengthened reproductive cycles, follicular arrest, hyper-androgenemia, and infertility." (PMID 27146259, 2016). "Similarly, another research showed that 8 weeks of Cr application in infertile women with PCOS could have a positive impact on glycemic control, decline of fasting insulin, HOMA-IR, TG, VLDL and total cholesterol, increase of antioxidant capacity, and improvement of oxidative stress." (PMID 33422126, 2021). "Statistically significant difference was observed between the PCOS, PCOS-infertile, PCOS-RPL women and non-PCOS groups based on age, BMI, insulin and Free T. The levels of TG and LH in the PCOS patients were significantly higher than in the non-PCOS women." (PMID 34407095, 2021). "Thus, the reduced insulin secretion induced by dietary adjustments is an attractive non-pharmacological treatment to prevent infertility, and a Mediterranean diet aimed at maintaining normal body mass may be effective in the preservation of ovarian health and physiology." (PMID 31231310, 2019).